TPO (thyroid peroxidase)
Diseases named in the same sentence as TPO in open-access papers (continued):
Sharing a sentence is not in itself a finding about the gene and the disease.
hypothyroidism (continued). "TPO abnormality is the most common cause of congenital dyshormonogenetic hypothyroidism where more than 60 mutations in the TPO gene that affect TPO activity to varying extents have been described." (PMID 24745015, 2014). "Thyroid peroxidase antibodies are found in 5–15% of women of childbearing age and account for the main cause of hypothyroidism seen in pregnancy." (PMID 23762775, 2013). "Whatever the underlying pathophysiological process is, the major factors contributing to hypothyroidism includes the female gender with a relative risk ranging between 3–7 times and the presence of anti-TPO antibodies (Ab)." (PMID 16219106, 2005). "Furthermore, estrogenic activity from isoflavonoids and thyroid peroxidase inhibition raise concerns for hypothyroidism development in iodine-deficient individuals." (PMID 41551427, 2026). "Additionally, isoflavonoids exhibit estrogenic activity and can inhibit thyroid peroxidase, raising concerns for hypothyroidism development, particularly in iodine-deficient or hypothyroid individuals." (PMID 41551427, 2026). "Furthermore, elevated anti-TPO levels are associated with a poorer prognosis and an increased risk of glandular failure, which explains the abrupt transition to biochemical hypothyroidism in our patient." (PMID 40772166, 2025). "They hypothesized that since anti-TPO cause hypothyroidism by thyrocyte damage from lymphocytic infiltration, this process would protect against relapse of GD after the cessation of ATD treatment." (PMID 40255503, 2025). "The impact of the presence of anti-TPO at diagnosis of GD on the risk of developing hypothyroidism after ATD remains unknown, information that is important for individualized treatment." (PMID 40255503, 2025). "Future studies with a larger sample size should explore whether elevated anti-TPO levels at the end of treatment, particularly in combination with normalized TRAb values, increase the risk of hypothyroidism." (PMID 40255503, 2025). "Notably, patients with SCH and high anti-TPO antibody titers are at greater risk of progressing to overt hypothyroidism." (PMID 39902025, 2025). "We hypothesized that anti-TPO at diagnosis of GD would decrease the risk of relapse following treatment while increasing the risk of hypothyroidism post-treatment." (PMID 40255503, 2025). "Hypothyroidism of congenital origin has been described in humans and several animal species, with dyshormonogenesis being a common cause, related to failures in the synthesis and function of TPO, due to the inability in the organification of iodine." (PMID 40013294, 2024). "The mechanisms of renal dysfunction in hypothyroidism include nephritis, such as membranous nephropathy and IgA nephropathy, which are associated with immunological mechanisms involving the deposition of thyroid peroxidase." (PMID 38416371, 2024). "Data on 211 bacterial taxa were obtained from the MiBioGen consortium, and data on thyroid dysfunction, including hypothyroidism, thyroid-stimulating hormone alteration, thyroxine deficiency, and thyroid peroxidase antibodies positivity, were derived from several databases." (PMID 38027113, 2023). "Hypothyroidism may also increase the risk of obesity, which is associated with a positive anti-TPO (antibodies directed against thyroid peroxidase) titer." (PMID 38138886, 2023). "Clinical thyroid disease, in particular, overt hypothyroidism, was seen to be of greater significance than thyroid autoimmunity for the risk of pregnancy loss among pregnant women with a prior history of miscarriage and positive anti-TPO." (PMID 37606882, 2023). "Therefore, thyroid stimulating hormone (TSH) levels, aTg and thyroid peroxidase (TPO) antibody testing is crucial in establishing the diagnosis of hypothyroidism or for evaluating risk." (PMID 36120277, 2022).
hypothyroidism (continued). "Thus, based on our and previous observations, the presence of TPO Ab at diagnosis represents a risk factor for the development of early hypothyroidism after administration of RAI." (PMID 35687484, 2022). "One hypothesis is a direct harmful effect of TPO-AB on ovarian tissue or hypothyroidism caused by autoimmunity, leading to infertility." (PMID 35453500, 2022). "Besides, in euthyroid patients, a positive TPO Ab status is associated with an increased risk for the development of hypothyroidism, and patients with silent or post-partum thyroiditis typically have elevated TPO Ab levels." (PMID 35687484, 2022). "For example, the inhibition of thyroperoxidase (TPO) enzyme, which catalyses the synthesis of thyroid hormones, may cause dysfunctions related to hypothyroidism." (PMID 34456728, 2021). "Single nucleotide polymorphisms (SNPs) associated with thyroid-stimulating hormone (TSH), free tetraiodothyronine (FT4), hyper- and hypothyroidism, and anti-thyroid peroxidase antibodies (TPOAb), from genome-wide association studies (GWAS), were selected as MR instrumental variables." (PMID 34945778, 2021). "Patients with HT have hypothyroidism due to thyroid gland damage, which is caused by an excessive inflammatory response against the thyroid gland, mediated by the auto-antibodies anti-thyroglobulin (anti-TG) and anti-thyroid peroxidase (anti-TPO)." (PMID 35366263, 2021). "The presence of TPO antibodies in autoimmune thyroid disease is associated with a long-term risk of hypothyroidism and their presence in GD is a key reason why patients are at risk of hypothyroidism after ATD is stopped." (PMID 34289872, 2021). "Moreover, hypothyroidism was determined, and TPO levels were significantly decreased with a higher risk of depression, which was expressed during gestation as a marker for subsequent postpartum depression." (PMID 32265710, 2020). "Moreover, the abnormal expression of TPO and the immune response associated with TPO-Ab are important mechanisms of thyroid cell injury in patients with hypothyroidism." (PMID 32461982, 2020). "Women with the lowest ovarian reserves had higher levels of TPO Ab, with a positive trend of this antibody overtime in comparison to other quartiles, indicating that this group may be at a higher risk of hypothyroidism over time." (PMID 31064360, 2019). "Furthermore, the presence of TPO autoantibodies is the strongest risk factor for both hyper- and hypothyroidism; smoking is negatively correlated with the presence of TPO antibodies." (PMID 30384852, 2018). "Therefore, this study aims to further investigate the association of anti-TPO antibodies and hypothyroidism with mothers’ preterm delivery." (PMID 30288165, 2017). "The decreased TSH could inhibit the expression of TPO gene, one of the causes of thyroid dyshormonogenesis leading to hypothyroidism characterized by normal synthesis of TH and aberrant protein expression as reported." (PMID 28713435, 2017). "Defects in the TPO gene are commonly inherited in an autosomal recessive pattern; therefore, differentiating the genetic basis of congenital hypothyroidism from other causes of hypothyroidism has important implications in terms of genetic counseling." (PMID 26761947, 2016). "Severe iron deficiency may lower thyroid peroxidase activity and interfere with the synthesis of thyroid hormones thereby leading to hypothyroidism." (PMID 26819633, 2016). "TPO gene abnormality is the most common cause of congenital dyshormonogenetic hypothyroidism." (PMID 24745015, 2014). "Thus, presence of TPO antibodies very often predicts the risk of hypothyroidism, and, in pregnant women with low serum TSH concentrations, hyperthyroidism will be predicted by TSHRAb in 60–70% of the cases." (PMID 23762775, 2013).
hypothyroidism (continued). "The overt disease is defined by the dramatic loss of thyroid follicular cells (thyrocytes), hypothyroidism, goitre, circulating autoantibodies to two primary thyroid-specific antigens, thyroglobulin (Tg), thyroid peroxidase (TPO), and lowered concentrations of serum TSH and T4." (PMID 15762980, 2005). "The key enzyme gene TPO (thyroid peroxidase) showed a positive correlation (β_SMR = 0.389, P_SMR = 1.95 × 10 − 9), suggesting that decreased expression of this gene is associated with increased hypothyroidism risk, possibly by directly affecting iodine activation and thyroxine production." (PMID 41570039, 2026). "Therefore, it could be theorized that anti-TPO may increase the risk of hypothyroidism after treatment of GD." (PMID 40255503, 2025). "In the Wolff-Chaikoff effect, there is a suppression of sodium/iodide symporter (NIS) and thyroid peroxidase; however, most individuals escape this effect within two days, and failure to escape, especially those with underlying autoimmunity (anti-TPO+), may lead to hypothyroidism." (PMID 40772166, 2025). "The aims of this study were to 1) investigate whether elevated anti-TPO levels at diagnosis of GD lower the risk of relapse after ATD or RI treatment, and 2) determine whether elevated anti-TPO levels at diagnosis of GD increase the risk of developing hypothyroidism after ATD treatment." (PMID 40255503, 2025). "Postpartum thyroiditis (PPT) is associated with autoantibodies to TPO, and the destructive autoimmune process may present clinically as transient hyperthyroidism, transient hypothyroidism, or hyperthyroidism followed by hypothyroidism and recovery." (PMID 39707289, 2024). "Furthermore, group B (< 100 m) was positively associated with autoimmune thyroiditis, thyroid peroxidase and thyroglobulin antibody positivity, and negatively associated with overt hypothyroidism, subclinical hypothyroidism, and goiter compared with the first ladder group(P < 0.05)." (PMID 38167020, 2024). "Thus, a significant model combined with TPO-Ab, TG-Ab, TG, and Fb may be used to screen high-risk populations for hypothyroidism after radiotherapy (AUC = 0.796)." (PMID 32461982, 2020). "Moreover, while TPO antibodies are clearly associated with increased risk of hypothyroidism, this finding could corroborate physiologically increased levels of TSH with aging." (PMID 31164997, 2019). "Previous reports of CH due to TG and TPO mutations most commonly involve biallelic mutations; therefore, it is unclear whether the mild or subclinical hypothyroidism was attributable to the monoallelic mutation or whether they harbored a second “hit” not detected by our sequencing methods." (PMID 27525530, 2016). "High serum antibodies against the enzyme thyroid peroxidase (TPO), which is located in the thyroid and plays a key role in thyroid hormone synthesis, are present in 90% of patients with Hashimoto's thyroiditis, the most frequent cause of hypothyroidism and goiter." (PMID 24586183, 2014). "One of the major causes of acquired hypothyroidism is chronic autoimmune thyroiditis (Hashimoto's Disease) in which laboratory testing may reveal auto-antibodies to the thyroglobulin protein (Anti-Tg), and the thyroid peroxidase enzyme (Anti-TPO)." (PMID 21073760, 2010). "This patient’s condition was characterized by the development of hypothyroidism and elevated anti-TPO antibodies post-radioiodine therapy." (PMID 40772166, 2025). "In the GESUS cohort, we identified 5,452 individuals with TSH, fT4 and anti-TPO measurements that were free of hypothyroidism at baseline." (PMID 41238958, 2025). "Among the mothers, 80 had hypothyroidism or subclinical hypothyroidism, four had hyperthyroidism (with TR-Ab positive in two mothers and TPO antibody positive in the other two), and four had thyroid nodules without thyroid function abnormalities." (PMID 40678318, 2025).
hypothyroidism (continued). "Twenty-five patients were TPO-Abs positive at diabetes onset, and 21 of them (84%) developed thyroid dysfunction (20 hypothyroidism, 1 Graves’ disease), after a median follow-up of 5 years (range, 0–25), at a mean age of 35 ± 13 years (range, 15–72)." (PMID 41255538, 2025). "As a result of the long-term influence of TPO-Ab as a competitive inhibitor of TPO action, hypothyroidism develops." (PMID 40137106, 2025). "Among the most frequently reported genes in exome sequencing, TPO was identified in two patients with compound heterozygosity, both presenting with hypothyroidism as their primary clinical concern." (PMID 40918675, 2025). "Data on age, gender, history of hypothyroidism, vitamin D, vitamin B12, anti-TPO, and anti-Tg levels were collected and analyzed." (PMID 41261692, 2025). "In Thy-BrafV600E mice, key molecules involved in thyroid hormone synthesis such as SLC5A5 (NIS), TPO and TG are apparently downregulated, thereby leading to severe hypothyroidism." (PMID 41152554, 2025). "A statistically significant correlation was found between vitamin D levels and HT, age, history of hypothyroidism, anti-TPO, anti-Tg, and vitamin B12 levels." (PMID 41261692, 2025). "This study demonstrates that AITD, as reflected by elevated anti-TPO antibody levels in the study subjects, is the predominant etiology of hypothyroidism." (PMID 41280993, 2025). "The process involves anti-TPO positive hypothyroidism leading to circulating immune complexes, deposition in renal tissues, complement activation, immune cell recruitment, and glomerular injury." (PMID 40937419, 2025). "Autoantibodies—particularly anti-TPO and anti-thyroglobulin (anti-Tg)—often appear several years before the development of biochemical or clinical hypothyroidism in HT." (PMID 41234630, 2025). "Thyroid peroxidase (TPO) antibodies and elevated cholesterol were identified as key predictors of progression to overt hypothyroidism." (PMID 40502886, 2025). "Often a few cases of hypothyroidism with increased anti-thyroid peroxidase were also reported with obvious improvement after treatment." (PMID 40886522, 2025). "A meta-analysis notes that hypothyroidism, the presence of anti-thyroglobulin antibodies, anti-thyroid microsomal antibodies, and anti-thyroid peroxidase antibodies are higher in HCV patients than in controls." (PMID 40868568, 2025). "When considered together, anti-Tg Abs positive patients or anti-TPO Abs positive patients showed a 20% increased proportion of progression to hypothyroidism (respectively 50% vs. 30%, p = 0.035)." (PMID 40362412, 2025). "Profound hypothyroidism, confirmed by markedly elevated thyroid-stimulating hormone (TSH) and anti-thyroid peroxidase antibodies, was identified as the underlying cause of the cardiac biomarker abnormalities." (PMID 41175858, 2025). "TPO tests are important in differentiating between thyroid disorders, including distinguishing hypothyroidism from Hashimoto’s thyroiditis." (PMID 38337667, 2024). "For cases of hypothyroidism, including TPO-antibody testing is prudent as it indicates an autoimmune origin." (PMID 38345684, 2024). "Among patients with SCH, there is a notable propensity for progression to clinically overt hypothyroidism, occurring at a rate of 2.6% annually in those with negative anti-TPO antibodies and 4.3% in those with positive anti-TPO antibodies." (PMID 38957249, 2024). "Anti-thyroid peroxidase antibodies (TPOAb) are able to cross the placenta but rarely induce hypothyroidism in the newborn, much less goiter." (PMID 38840805, 2024). "The autoimmune facet of hypothyroidism is characterized by the infiltration of T lymphocytes into the thyroid gland and autoantibodies against thyroid-specific genes (e.g., thyroid peroxidase, thyroglobulin, and TSH receptor)." (PMID 38919955, 2024).
hypothyroidism (continued). "A possible reason for this condition is the concomitant hypothyroidism indicated by the increases in both the anti-thyroglobulin and thyroid peroxidase antibodies titers with the TSH-receptor antibodies level being in the normal range." (PMID 40729266, 2024). "Among the women with TS who had hypothyroidism, 14% had elevated TPO compared with 1% of women with hypothyroidism in the general population sample (P < .0001)." (PMID 37758506, 2024). "Laboratory results also revealed an increase in both anti-thyroglobulin and thyroid peroxidase antibody titers with concomitant level of TSH-receptor antibodies in the normal range underscoring a condition of hypothyroidism." (PMID 40729266, 2024). "It is characterized by chronic inflammation and the presence of autoantibodies targeting thyroid peroxidase (TPO) and thyroglobulin (TG), resulting in hypothyroidism and frequently leading to the degeneration of the thyroid gland." (PMID 39469463, 2024). "Specifically, anti-TPO antibodies were present in 17 (21.25%) participants, with the highest occurrence in those with hypothyroidism, seen in nine (11.25%) participants." (PMID 39221289, 2024). "The prevalence of positive anti-TPO antibodies in SCH correlates with autoimmune thyroiditis as the primary etiology of hypothyroidism." (PMID 38957249, 2024). "The correlation between vitiligo and positive TPO antibodies, hypothyroidism, and autoimmune thyroiditis is notably high." (PMID 39429364, 2024). "We recently reported greater changes in thyroid autoantibody (anti-thyroglobulin and anti-thyroid peroxidase antibodies) titers from baseline to irAE onset in patients with thyrotoxicosis than in those with isolated hypothyroidism." (PMID 39574956, 2024). "The correlation between vitiligo and positive thyroid peroxidase antibodies, hypothyroidism, and autoimmune thyroiditis is notably high." (PMID 39429364, 2024). "The most ordered tests in the diagnosis and treatment of hypothyroidism are thyroid peroxidase antibodies (anti-TPO) and thyroglobulin antibodies." (PMID 39264098, 2024). "One of the two homozygotes in the Qatar Biobank was asymptomatic at the age of 46 years, and the other suffered from hypothyroidism with autoantibodies against thyroid peroxidase (TPO) at the age of 31 years." (PMID 38422122, 2024). "Given her known history of hypothyroidism and ongoing psychiatric symptoms, thyroid function tests (TFTs) and anti-TPO antibody testing were ordered alongside other routine laboratory investigations." (PMID 39539911, 2024). "The analysis of the anti-TPO antibody revealed the positive association between the anti-TPO value and the serum concentrations of visfatin and resistin in the T2DM patients with hypothyroidism." (PMID 36830883, 2023). "The impact of independent variables (ID, age, and BMI) on the dependent outcome measures (subclinical hypothyroidism and elevated anti-TPO) was explored using fitting logistic regression models in the present study." (PMID 36636539, 2023). "Correlation between ID and hypothyroidism is likely due to impaired thyroperoxidase (TPO) hemoprotein biosynthesis, as shown in a rat study in which ID reduced TPO activity." (PMID 38004184, 2023). "Those patients who developed hypothyroidism while on treatment were observed to have low anti-TPO Abs titers (≤5 IU/mL; odd ratio = 3.353, sensitivity = 16%, specificity = 94%, p=0.040)." (PMID 37123800, 2023). "Previous studies have noted that individuals who developed early hypothyroidism had higher levels of TSH before surgery and a higher occurrence of thyroid peroxidase antibody positivity compared to those who experienced late-onset hypothyroidism." (PMID 38116025, 2023). "Patients with hypothyroidism (25%) showed anti-thyroid peroxidase (anti-TPO) antibody positivity, indicating an autoimmune mechanism underlying the thyroid dysfunction." (PMID 37664252, 2023).